DGAT1 (diacylglycerol O-acyltransferase 1)
Diseases named in the same sentence as DGAT1 in open-access papers (continued):
Sharing a sentence is not in itself a finding about the gene and the disease.
breast carcinoma (12 papers, 2018 to 2025). "Further, DGAT1 amplification in a large breast cancer cohort was associated with a significant decrease in overall survival." (PMID 30099850, 2018). "DGAT-1, a major enzyme in the synthesis of triglycerides, has been observed to be overexpressed in breast cancer cells." (PMID 40002245, 2025). "Inhibition of DGAT1 activity by a DGAT1 inhibitor (A922500) significantly reduced TG synthesis, cell proliferation, and the migratory ability of breast cancer MDA-231 cells, accompanied by decreased expression levels of cyclin D1 and Zeb1." (PMID 38500157, 2024). "The expression of DGAT1, DUT, LYPLA1, and POLR2K was linked to an increased risk of breast cancer, whereas SMPD4 was associated with a protective effect." (PMID 37644433, 2023). "Analysis of the METABRIC breast cancer cohort showed DGAT1 amplification in 21% (434/2051) of breast cancer samples." (PMID 30099850, 2018). "Interestingly, the prevention of LD accumulation in Elovl5-silenced MCF-7 cells by a treatment with DGAT1 inhibitor reduced lung metastases in mice highlighting a therapeutic role of anti-lipid-droplet drugs against breast cancer metastasis." (PMID 36056008, 2022). "In addition, the genes flanking either orientation, the ZC3H3 and DGAT1, were upregulated in breast cancer." (PMID 36497066, 2022). "Likewise, a DGAT1 inhibitor (T-863 or PF-04620110) significantly decreased the total number of small and large LDs in breast cancer MCF-7 cells, suggesting that DGAT1 and DGAT2 interact in the process of LD formation in tumor cells." (PMID 38500157, 2024). "Treatments with inhibitors of DGAT1 (A922500, DGAT1i) and DGAT2 (PF-06424439, DGAT2i) activity for 48 h were able to counteract the increase of plasma membrane TGFβ-R1 and TGFβ-R2 levels in Elovl5-depleted breast cancer cells." (PMID 36056008, 2022).
diabetes (12 papers, 2012 to 2024). "Diabetes enhanced the expression of resistin and DGAT1 in epididymal fat pad (P < 0.05); however, pepino intake significantly suppressed mRNA expression of resistin and DGAT1 in epididymal fat pad (P < 0.05)." (PMID 24527264, 2012).
type 2 diabetes (11 papers, 2006 to 2025). "Phase IIb clinical trial results for a DGAT1 inhibitor in obese patients with type 2 diabetes were recently reported, which showed modest reductions in HbA1c and body weight." (PMID 23336002, 2013). "The results of our current study further revealed that pepino treatment improved hyperglycemia and hyperinsulinemia, reduced cardiac oxidative stress and lipid accumulation in circulation and tissues, and regulated resistin and DGAT1 in type 2 diabetic mice." (PMID 24527264, 2012). "PF-04620110 was the first pharmacological inhibitor of DGAT1 tested in healthy humans and patients with type 2 diabetes, and this drug demonstrated a dose-dependent reduction of postprandial TG excursions with varying degrees of gastrointestinal adverse effects (NCT01298518)." (PMID 38500157, 2024). "This suggests that to treat type 2 diabetes with an inhibitor of DGAT1 it may be necessary to inhibit activity markedly." (PMID 17239230, 2007). "We showed for instance that preventing LD formation in cancer cells facing an acidic pH with a DGAT1 inhibitor represents an achievable goal to limit invasion, offering a rationale for the repurposing of such drugs currently under clinical evaluation for the treatment of type 2 diabetes and obesity." (PMID 31974393, 2020). "In a Type 2 diabetic mouse model, Pfizer's PF‐04620110 has been shown to lower blood TAG levels and inflammation by specifically inhibiting DGAT1." (PMID 40251888, 2025).
hepatoma (10 papers, 2016 to 2025). "This is in line with the downregulation of DGAT1 in PHG, as DGAT1 overexpression is associated with higher rates of very-low-density lipoprotein-TG complex secretion from rat hepatoma cells." (PMID 37414142, 2023). "The stem cell‐like behaviours caused by complete and long‐term silencing of DGAT1 were also observed in another hepatocellular carcinoma cell line, HepG2." (PMID 26493024, 2016). "Again, the underlying mechanisms how human hepatoma cells become dedifferentiated after DGAT1‐silencing remains to be elucidated." (PMID 26493024, 2016). "Moreover, in HCV packaging, DGAT1 activity fostered the association of core protein with LDs, and treatments with DGAT1 inhibitor reduced such association and, consequently, the infectious viral particle production in hepatoma cells." (PMID 33134318, 2020). "In this study, we discovered that complete and long‐term silencing of DGAT1 directed two different hepatoma cell lines, Huh‐7.5 and HepG2, towards a dedifferentiated and stem cell‐like phenotype." (PMID 26493024, 2016). "To reinforce general significance, we examined spheroid formation, proliferation and expression level of adhesion molecules after DGAT1 silencing in another hepatoma cell line, HepG2 cells." (PMID 26493024, 2016). "Hence, in Drosophila and rat hepatoma cells, many small or fewer large LDs accumulate respectively upon DGAT1 and DGAT2 overexpression." (PMID 39241103, 2024). "While MTP-dependent transfer of neutral lipids is dispensable for ApoE secretion, TG biosynthesis, redundantly catalyzed by DGAT1 and DGAT2, is required for efficient ApoE secretion in hepatoma cells." (PMID 40180213, 2025). "Taken together, our data suggest a proviral role for DGAT1 and SOAT1 in ZIKV infection in hepatoma cells." (PMID 39237833, 2024). "In line with this, viral nucleocapsid protein has also been shown to induce DGAT1 and DGAT2 expression in the human hepatoma cell line Huh7, as evidenced by a reporter gene assay." (PMID 37113005, 2023). "Indeed, a previous study revealed that DGAT1 recycles the products of TG hydrolysis, which are partial glycerides, for TG synthesis, meaning that DGAT1 is involved not only in TG biosynthesis but also in the overall regulation of intracellular lipid status at least in human hepatoma cells." (PMID 26493024, 2016). "Collectively, it can be inferred that DGAT1 and DGAT2 have different roles, and DGAT1 takes critical role of maintaining intracellular lipid homoeostasis in human hepatoma cells." (PMID 26493024, 2016). "However, we found both ApoB and ApoE require nascent biosynthesis of TGs catalyzed by redundant activities of both DGAT1 and DGAT2 for their efficient expression and secretion by the hepatoma cells." (PMID 40180213, 2025). "This latter observation was not seen in H4IIEC3 rat hepatoma cells when inhibiting TAG synthesis through siRNA silencing of DGAT1 and DGAT2." (PMID 30099850, 2018). "Downregulation of DGAT1 and SOAT1 compromises ZIKV infection in hepatoma cells but only SOAT1 and not DGAT inhibitor treatment reduces ZIKV infection." (PMID 39237833, 2024).
dyslipidemia (8 papers, 2012 to 2025). "Inhibition of either DGAT1 or DGAT2 has been considered to be an attractive target for the treatment of dyslipidemia." (PMID 30333041, 2018). "Therefore, DGAT1 has been considered to be a potential target for treating T2D and dyslipidemia." (PMID 35681388, 2022). "On the other hand, DGAT1 inhibition likely has additional GLP-1-independent therapeutic benefits, such as improving dyslipidemia." (PMID 23336002, 2013).
hypertriglyceridemia (8 papers, 2014 to 2024). A laboratory test result indicating elevated triglyceride concentration in the blood. "Hypertriglyceridemia appears to be a feature of human DGAT1 deficiency and possibly is due to increased hepatic TG secretion mediated by DGAT2 and/or to impaired clearance of TG-rich lipoproteins." (PMID 28373485, 2017). "The cause of diarrhea with protein-losing enteropathy, and in most cases hypertriglyceridemia, with DGAT1 deficiency is unknown." (PMID 28373485, 2017). "These favorable metabolic effects motivated the development of numerous DGAT1 inhibitors as therapeutic agents to treat hypertriglyceridemia or other obesity-related diseases." (PMID 28373485, 2017). "The aim of this research was to identify a botanical extract that inhibits intestinal DGAT1 activity and attenuates postprandial hypertriglyceridemia in overweight and obese humans." (PMID 26246845, 2015). "Hence, it may be speculated that the miR-122-5p down-regulation observed in the HIV+ SC adipose tissue may increase the expression of DGAT1 as well as TG synthesis, which ultimately may result in hypertriglyceridemia, one of the conditions affecting HALS patients." (PMID 35408847, 2022).
melanoma (8 papers, 2022 to 2025). A malignant, usually aggressive tumor composed of atypical, neoplastic melanocytes. "Plotting expression fold change against association with patient survival, dgat1a/DGAT1 emerged as an outlier, being both highly up-regulated in zebrafish melanoma and significantly associated with reduced patient survival." (PMID 35732120, 2022). "In melanoma cells, DGAT1 inhibition caused excess FA oxidation and ROS generation, accompanied by activation of nuclear factor erythroid 2-related factor 2 (NRF2) signaling, which reduces ROS-mediated cellular damage through upregulation of superoxide dismutase 1 (SOD1)." (PMID 36776554, 2023). "We next considered what might underlie DGAT1 up-regulation in melanoma." (PMID 35732120, 2022). "To assess if this applies to human melanoma cells, we treated our panel of human melanoma cell lines with the DGAT1 inhibitor in nutrient limited media and measured proliferation." (PMID 37268606, 2023). "Combined DGAT1 and SOD1 suppression caused fatal ROS overload and melanoma cell death, as well as suppressed tumor growth." (PMID 36776554, 2023). "For example, the key lipid droplet protein DGAT1 promotes melanoma growth, and our data using the Plin2 lipid droplet reporter suggest that this is likely increased in the Agrp animals." (PMID 36472402, 2023). "The significant impact of DGAT1 antagonism on melanoma cell proliferation and survival, exacerbated under conditions mimicking tumor microenvironmental stresses, highlights DGAT1 as a possible therapeutic target in melanoma." (PMID 35732120, 2022). "Forced expression of DGAT1 in the DGAT1Low melanoma cell line 888MEL led to an increase in cellular proliferation in all four clones tested." (PMID 35732120, 2022). "DGAT1 is pan-cancer amplified, and it remains to be determined to what extent other cancers can mount the anti-ROS responses we observed in our melanoma xenograft models." (PMID 35732120, 2022). "We observed increasing ROS production over time upon DGAT1 inhibition in multiple melanoma cell lines." (PMID 35732120, 2022). "We uncovered frequent DGAT1 amplification and up-regulation in melanoma but also in many other cancers, notably ovarian, breast, uterine, esophageal, liver, pancreatic, head and neck, prostate, stomach, and lung cancers." (PMID 35732120, 2022). "In human melanoma, DGAT1 amplification was observed to co-occur with BRAF and NRAS mutation but also independently of either." (PMID 35732120, 2022). "We therefore investigated the role of DGAT1 over-expression in allowing melanoma cells to tolerate nutrient and oxygen deprivation in culture." (PMID 35732120, 2022). "We now demonstrate that DGAT1 is a bona fide metabolism oncoprotein that stimulates melanoma tumorigenesis by conferring protection against ROS, including lipid peroxidation, through inducing LD formation (see model)." (PMID 35732120, 2022). "Taking these results together, we conclude that DGAT1 maintains mitochondrial function in melanoma cells by regulating the availability of FA for FAO." (PMID 35732120, 2022). "find that DGAT1, which stimulates triglyceride and lipid droplet formation, is a melanoma oncoprotein." (PMID 35732120, 2022). "Further highlighting the key role of DGAT1 up-regulation in melanoma cells, even under standard tissue culture conditions, siRNA knockdown or pharmacological inhibition of DGAT1 led to apoptosis, quantified through an increase in cleaved caspase-3." (PMID 35732120, 2022). "DGAT1-overexpressing melanoma cells exhibited a 100%–200% increase in cell number compared with parental DGAT1Low cells under conditions of greatest stress: 1% serum and hypoxia (1% O2)." (PMID 35732120, 2022). "Having uncovered DGAT1 as an oncoprotein, we next assessed the impact of DGAT1 antagonism in human melanoma cell lines." (PMID 35732120, 2022).
melanoma (continued). "Here, we demonstrate that diacylglycerol O-acyltransferase 1 (DGAT1), an enzyme integral to triacylglyceride synthesis and lipid droplet formation, is frequently up-regulated in melanoma, allowing melanoma cells to tolerate excess FA." (PMID 35732120, 2022). "Here, we demonstrate the oncogenic ability of DGAT1 in melanoma using zebrafish and find that DGAT1 again exerts this effect primarily through shielding melanoma cells from lipotoxicity." (PMID 35732120, 2022). "We implanted DGAT1High A375 melanoma cells in mouse flanks and commenced daily oral treatment with the DGAT1 inhibitor A922500 (90 mg/kg/day) when tumors reached approximately 100 mm3." (PMID 35732120, 2022). "Over-expression of DGAT1 in human melanoma cells resulted in a striking increase in LD, consistent with cells adopting an engorged morphology." (PMID 35732120, 2022). "An extra copy of chromosome 8q, containing the DGAT1 locus but also other putative melanoma oncogenes ASAP1/DDEF, MYC, and GDF6, has been observed in approximately 30% of melanoma cases." (PMID 35732120, 2022). "Antagonism of DGAT1 induces oxidative stress in melanoma cells, which adapt by up-regulating cellular reactive oxygen species defenses." (PMID 35732120, 2022). "A positive association of DGAT1 and cancer growth was confirmed in vivo in zebrafish melanocytes 21, in which DGAT1 overexpression induced melanoma growth, and also in a xenograft model of GBM in mice, in which both genetic and pharmacological suppression of DGAT1 inhibited GBM growth." (PMID 40083687, 2025). "Upregulation of DGAT1 could also be observed in melanoma, which was correlated with reduced patient survival, selective DGAT1 inhibitors suppressed lipid droplets formation and suppressed melanoma cell growth." (PMID 40554491, 2025). "To test whether lipid droplet loss disrupts glycolytic and mitochondrial oxidative function in melanoma cells, we inhibited DGAT1 in human melanoma cell lines in nutrient-limited media and performed the Seahorse ATP Rate Assay." (PMID 37268606, 2023). "Our study relied on established human melanoma cell lines to explore DGAT1 function, and these may have adapted to ex vivo culture in ways that make them less representative than primary cells." (PMID 35732120, 2022). "Potentially, PDX models, autochthonous genetically engineered mouse melanoma models, or ex vivo tumor explant culture might have allowed us to maintain more features of melanoma in which to assess the impact of DGAT1 depletion or antagonism." (PMID 35732120, 2022). "To address the effect of DGAT1 on melanoma lipid metabolism, we performed ultra-high-performance liquid chromatography-mass spectrometry (UHPLC-MS) to identify and contrast lipid species extracted from NRASG12D Dgat1a-over-expressing or NRASG12D EGFP-expressing zebrafish tumors." (PMID 35732120, 2022). "Conversely, we observed decreased 4HNE protein conjugation in DGAT1-over-expressing melanoma cells and in zebrafish tumors over-expressing Dgat1a, indicating that lipid peroxidation and its suppression by DGAT1 occurs not only in cell lines but also within tumors." (PMID 35732120, 2022). "In human melanoma models, DGAT1 also exhibited oncogenic characteristics." (PMID 35732120, 2022). "Consequently, DGAT1 inhibition results in oxidative stress in melanoma cells but this is countered by adaptive up-regulation of ROS-neutralizing enzymes such as superoxide dismutase 1 (SOD1)." (PMID 35732120, 2022). "Thus, DGAT1 promotes the survival of melanoma cells by suppressing the ROS production and lipid peroxidation that would otherwise occur as a result of their increased FA acquisition." (PMID 35732120, 2022).
melanoma (continued). "We next investigated whether ROS induction upon DGAT1 suppression affected melanoma cell survival." (PMID 35732120, 2022). "Thus, in zebrafish, Dgat1 behaves as a melanoma oncoprotein." (PMID 35732120, 2022). "Assuming that ROS-neutralizing factors such as SOD enzymes were limiting the tumor inhibitory effects of DGAT1 antagonism, we next examined whether blocking the induction of SOD1 would augment the impact of DGAT1 inhibition on melanoma cell growth and survival." (PMID 35732120, 2022). "Similarly to siRNA-mediated depletion, pharmacological antagonism of DGAT1 suppressed growth of DGAT1High (A375, MM485, and SKMEL105) and DGAT1Amplified (LOXIMVI and SKMEL5) melanoma cells over 96 h, accompanied by decreased cell cycle progression." (PMID 35732120, 2022). "Consistently, DGAT1, ASAP1, MYC, and GDF6 are co-amplified in melanoma and other cancers." (PMID 35732120, 2022). "Thus, combinatorial DGAT1 and SOD1 inhibition synergized to create a toxic overload of ROS in tumors, severely retarding the growth of melanoma cells in vivo." (PMID 35732120, 2022). "Combinatorial DGAT1 and SOD1 inhibition led to a profound impairment of melanoma growth in vivo." (PMID 35732120, 2022). "However, we did not observe efficacy of DGAT1 inhibition alone in our mouse melanoma xenograft models, most likely due to a striking upregulation of the anti-ROS response." (PMID 35732120, 2022). "Furthermore, we confirmed elevated expression of human DGAT1 but not DGAT2 mRNA in melanoma tumors relative to both skin and nevi and elevated DGAT1 protein in human melanoma cell lines relative to primary melanocytes irrespective of NRAS or BRAF mutational status." (PMID 35732120, 2022).